CD1D (CD1d molecule)
Diseases named in the same sentence as CD1D in open-access papers (continued):
Sharing a sentence is not in itself a finding about the gene and the disease.
tumor (246 papers, 2006 to 2026). "Allo15BCAR-NKT cells effectively and selectively depleted tumor-associated macrophages and MDSCs, corresponding to the high CD1d expression on these cells." (PMID 38744947, 2025). "Two major structural categories of tumor-associated lipids, phospholipids and sphingolipids with or without glycosylated modification, are sampled by human CD1d protein and function as agonists or antagonists for NKT cell responses." (PMID 40746558, 2025). "We have previously investigated the role of the tumor-associated ganglioside GD3 in inhibiting CD1d-dependent NKT cell activation." (PMID 39596374, 2024). "Despite limited CD1d expression in most human tumors, tumor-associated macrophages (TAMs) in various cancers do express CD1d, allowing iNKT cells to either lyse or remodel these TAMs to enhance antitumor responses." (PMID 38665921, 2024). "The anti-tumour effect of iNKT cells is further enhanced by their ability to eliminate tumour-associated macrophages on a CD1d-dependent manner." (PMID 36936927, 2023). "A reasonable conclusion would be that reduction in CD1d recycling leads to reduced NKT activation because tumor-associated lipids are unable to be loaded for presentation to NKT cells." (PMID 37908366, 2023). "CD1d is another tumor-associated antigen which can be targeted in CLL with a CD1d-specific Vγ9Vδ2-T cell engager made by single-domain antibodies (VHH)." (PMID 37143664, 2023). "It has been shown that iNKT cells can indirectly control tumor growth through targeting tumor-supportive, IL-6-producing, CD1d+ CD68+ tumor-associated macrophages (TAM)." (PMID 35784290, 2022). "iNKT cell immunosurveillance is likely mediated by inflammatory cytokines or recognition of tumor-associated glycolipids or stress-induced glycolipid antigens presented by CD1d positive tumor cells, or by antigen-presenting cells (APCs)." (PMID 34680322, 2021). "Due to limited variation within the human CD1D gene (which encodes CD1d), such strategies can also be applied to enhance the tumor-directed functions of allogeneic iNKT cells isolated from healthy donors." (PMID 32560408, 2020). "NKT cells possess the ability to recognize and lyse tumor-associated macrophages (TAMs) via their TCR binding CD1d, improving tumor invasion and clearing the path for other cell types to follow up." (PMID 32429316, 2020). "Invariant NKTs mediate their anti-tumor effects via various mechanisms, including direct cytotoxicity against CD1d+ tumor cells or tumor-associated macrophages." (PMID 32560408, 2020). "Particularly, GD3 expressed on melanoma is known to activate both CD4+CD8− NKT and CD4−CD8− NKT cells to produce IL-4, whereas CD4− CD8− NKT cells also react with GM3 as a tumor-associated suppressive glycolipid in a CD1d-restricted manner." (PMID 32231116, 2020). "Their counts inversely correlated with disease progression, which was linked to decreasing CD1d expression on the tumor cells as the disease progressed." (PMID 33680931, 2020). "While some CD1d-expressing tumors can probably cause Th1-biased iNKT cell activation, progressive chronic tumor cell growth can also apparently directly cause Th2-biased iNKT cell activation." (PMID 29559971, 2018). "In tumor immunity, CD1d-restricted type I NKT cells are also associated with the promotion of immune response against tumors." (PMID 29599785, 2018). "CD1d expression on tumor cells was associated with the induction of immunosuppressive functions in iNKT cells or the induction of “non-functional” iNKT cells." (PMID 29375569, 2017). "In this instance, higher presentation of tumor-associated lipids on CD1d by leukemic cells was suggested to cause iNKT cell hyporesponsiveness attributed to an impairment of CD3ζ signaling." (PMID 29109728, 2017). "Expression of high levels of Fas Ligand, perforin, and granzyme B by iNKT cells underlies their cytolytic activity against CD1d+ tumor cells and myeloid cells with immunosuppressive function present in the tumor microenvironment." (PMID 25349699, 2014).
tumor (continued). "As alternatives to tumor-associated markers, antigens over-expressed in the tumor stroma and/or neo-vessels would be additional good candidates for the targeting of CD1d molecules to the tumor site." (PMID 23242316, 2013). "Here, we demonstrate that CD1d fusion proteins bound to tumor cells via the antibody fragment specific for a tumor-associated antigen, efficiently activate human iNKT cell lines leading to potent tumor cell lysis." (PMID 23242316, 2013). "Intriguingly, iNKT cells have also been shown to specifically target the killing of CD1d-positive tumor-associated macrophages (TAMs), a highly plastic subset of inflammatory cells derived from circulating monocytes that perform immunosuppressive functions." (PMID 23118781, 2012). "Previous studies have demonstrated the ability of in vivo anti-CD1d antibody blockade to inhibit tumor progression of CD1d-deficient tumors." (PMID 21695190, 2011). "In this study, we found that long-term, low-dose HMA treatment upregulated CD70, NK receptor ligands, and CD1d on AML tumor cells, rendering them more susceptible to chimeric antigen receptor (CAR)-engineered invariant natural killer T (CAR-NKT) cell-mediated cytotoxicity." (PMID 41888396, 2026). "Of note, due to the limitations of the NSG model, our work does not address previously reported indirect antitumor effects of iNKT cell–based immunotherapy, including depletion of CD1d-expressing immunosuppressive, tumor-associated myeloid cells, and activation of antitumor T- and NK-cell responses." (PMID 40898981, 2026). "In addition, they actively modulate the tumor microenvironment by targeting CD1d+ tumor-associated macrophages." (PMID 42293340, 2026). "Notably, in tumors such as neuroblastoma, iNKT cells can kill CD1d+ tumor-associated macrophages (TAMs) and convert M2-like suppressive macrophages into pro-inflammatory M1-like macrophages, thereby mitigating TME-mediated immune suppression." (PMID 41194129, 2025). "iNKT cell activation can occur via multiple mechanisms—either indirectly, through cytokines or CD1d+ antigen-presenting cells (APCs) such as dendritic cells (DCs), macrophages, or B cells, or directly, by recognition of tumor-associated glycolipid antigens presented by CD1d-expressing tumor cells." (PMID 41194129, 2025). "The CD1d molecules on tumour cells bind and present endogenous tumour-associated glycolipids." (PMID 37153585, 2023). "Thus, iNKTs are rapidly cytotoxic and strongly modulate the tumor microenvironment by direct targeting of CD1d+ tumors, tumor-associated macrophages and myeloid-derived suppressor cells." (PMID 33262761, 2020). "Interestingly, ATC was associated with a significantly higher number of CD1d‐positive cells compared to other tumor entities and normal thyroid tissue." (PMID 31560833, 2019). "Besides active skewing of iNKT function via interaction with CD1d on tumor cells, some tumors escape from iNKT cell lysis by loss of CD1d expression and shedding of glycolipids, such as gangliotriaosylceramide which can inhibit iNKT stimulation." (PMID 30298063, 2018). "Besides providing a pro-inflammatory status by interaction with DCs, NK and CTL, iNKT have also been found to be able to control tumor growth by killing tumor supportive IL-6-producing CD1d+ CD68+ tumor associated macrophages (TAM)." (PMID 30298063, 2018). "Also, iNKT cells retained their ability to kill tumor-associated macrophages as a result of TCR-mediated recognition of CD1d." (PMID 30013569, 2018). "In both models, we could demonstrate a significant inhibition of tumor growth, which was dependent on the presence of iNKT and NK cells as the antitumor effects were abolished in CD1d-deficient mice or upon depletion of NK cells." (PMID 29163493, 2017). "However, the tumor-associated ganglioside GD3 can be presented on CD1d for the activation of iNKT cells in vivo." (PMID 29109728, 2017).
tumor (continued). "For example, tumor-associated monocytes and macrophages, which are associated with poor prognosis in neuroblastoma patients, were found to express CD1d and could be targeted by iNKT cells in a mouse model." (PMID 26052329, 2015). "Tumor cells expressing CD1d may be especially susceptible to direct NKT cell lysis, as shown in vitro." (PMID 25389427, 2014). "Importantly, all of these tumor models are CD1d-deficient, and the role of CD1d-expressing tumors in promoting a type I vs. type II NKT immune response in non-hematopoietic tumors has not previously been investigated." (PMID 21695190, 2011). "Also in this model, CD1d KO mice were highly resistant to tumor progression of both CD1d-expressing and CD1d-deficient tumor cells, suggesting a dominance of suppressive type II NKT cells." (PMID 21695190, 2011). "Interestingly, by comparing tumor growth of CD1d-expressing and CD1d-deficient tumor cells in NKT-deficient transgenic knockout (KO) models, we have uncovered important differences in the regulation of these cells by type I and type II NKT cells." (PMID 21695190, 2011). "Therefore, it is proposed that C. crescentus triggers the innate immune response, stimulates CD1d recognition and presentation of tumor associated antigens by DCs, activating NKT cells to produce IFN and resulting in immunosurveillance that responds to tumor cells expressing CD1d." (PMID 37514190, 2023). "In the future, NKT engineering with CARs could result in an enhanced antitumor efficacy in solid tumor settings, exploiting the synergism of CAR activity with their capability to kill immunosuppressive CD1d-expressing tumor-associated macrophages (TAMs) and myeloid-derived suppressor cells." (PMID 31212634, 2019). "Their invariant CD1d-restricted TCR reduces the risk of GVHD, and MHC-independent recognition helps prevent off-tumour effects." (PMID 41559435, 2026). "This restriction allows CAR-NKT cells to be engineered with CARs targeting TAAs and to harness their natural ability to detect lipids presented by CD1d, broadening their effectiveness against tumours that escape standard MHC-based immunity." (PMID 41559435, 2026). "For NKT cells, additional hurdles involve low cell counts, restricted infiltration, and reliance on CD1d expression by tumour or stromal cells." (PMID 41559435, 2026). "In parallel, chimeric antigen receptor (CAR)-engineered iNKT cells provide antigen-specific tumor targeting while preserving intrinsic CD1d-restricted immunomodulatory functions, demonstrating encouraging safety and efficacy in early-phase studies." (PMID 41898393, 2026). "Despite the CD1d negativity of most solid tumors, the anti-tumor potential of NKT cells has been demonstrated in many cancer models." (PMID 39995672, 2025). "Activated iNKT cells can directly kill CD1d+ tumor cells by releasing perforin and granzyme B, as well as through Fas/FasL interactions." (PMID 40698085, 2025). "This is interesting, given that RCC tumor expression of CD1d, the molecule that presents ligands to NKT cells, has been found to correlate with aggressive disease." (PMID 39773530, 2025). "These engineered cells display the α-GalCer–CD1d complex externally and incorporate tumor antigens (e.g., OVA, MART-1, Trp2, or WT1) internally." (PMID 40297580, 2025). "Direct tumor toxicity, promoted by the recognition of CD1d-presented lipid antigens, is mediated by perforins, granzyme B, and over-expression of the Fas ligand." (PMID 40002679, 2025). "iNKT cells are unique in their ability to recognize glycolipid antigens presented by CD1d molecules on the surface of tumor and antigen-presenting cells." (PMID 39941775, 2025). "Quantitative analysis of bioluminescence flux confirmed these findings, demonstrating the most tumor cell death in the iMRAS conjugated with CD1d/αGC+IL-15Tx group." (PMID 40297706, 2025).
tumor (continued). "Human CAR iNKT cells have demonstrated potent antitumor activity in vivo, eradicating tumor cells in a preclinical neuroblastoma model in immunodeficient mice, while retaining their physiological iTCR specificity for human CD1d-presented lipids in vitro." (PMID 41583436, 2025). "Fluorescent microscopy and bioluminescence imaging revealed significantly enhanced tumor cell killing in the group treated with iMRAS conjugated with CD1d/αGC+IL-15Tx compared to other conjugation strategies, including control and CD1d-only treatments." (PMID 40297706, 2025). "These cells recognize the CD1d molecule and exhibit potent tumor-killing capabilities, tumor infiltration, and the ability to bridge innate and adaptive immunity, making them promising candidates for new cancer treatment." (PMID 40260236, 2025). "Tumor-restricted lipid in vitro promotes and activates human iNKT cells via CD1d presenting B cells." (PMID 40746558, 2025). "iNKT cells kill CD1d+ tumor cells directly in a CD1d-dependent, Fas/FasL-mediated fashion and indirectly by stimulating NK and CD8 T cells via IFN-γ to attack tumors." (PMID 41148807, 2025). "iNKT cells can detect self-lipid antigens generated within the tumor lipidome, which are presented by CD1d." (PMID 41148807, 2025). "Further assessments in racotumomab-alum-treated patients should consider the characterization of these cells and of the CD1d expression at the tumor site." (PMID 40426949, 2025). "CL increases oxidative phosphorylation, supports tumor cell growth or mitochondrial degradation, leading to CL CD1d presentation (HCC)." (PMID 40746558, 2025). "This heightened cytotoxic response suggests that Decitabine-treated tumor cells are more susceptible to Allo15CAR33-NKT cell-mediated killing, likely due to the upregulation of NKR ligands and CD1d on the tumor cells." (PMID 39893165, 2025). "Meanwhile, Allo15BCAR-NKT cells killed tumor cells more effectively in the presence of CD1d/αGC, indicating a TCR-directed targeting mechanism." (PMID 38744947, 2025). "Mechanistically, NKT cells can directly target CD1d+ malignant cells and eliminate protumorigenic macrophages, reshaping immunosuppressive niches within the tumor microenvironment." (PMID 41583436, 2025). "CD1d-mediated interactions between iNKT cells and other immune populations also shape anti-tumor responses, sometimes in unexpected ways." (PMID 40718496, 2025). "Epigenetic modifications such as methylation of the TME can impact genes like beta-2-microglobulin (β2M) and Spi-1-proto-oncogene (SPI1), which control CD1D expression that is crucial for tumor antigen presentation and immune recognition." (PMID 40872475, 2025). "Although many solid tumors are associated with CD1d downregulation as a mechanism of immune escape, CAR-mediated recognition of the tumor-associated antigen restores their function in the tumor microenvironment." (PMID 40002679, 2025). "iNKT cells, recognizing CD1d molecules on tumor cell surfaces, trigger cytotoxic responses that eliminate tumor cells and concurrently enhance the effectiveness of chemotherapeutic agents." (PMID 38915446, 2024). "The co-expression of BCMA, CD1d, and NK ligands was identified on MM tumor cells across all the samples." (PMID 38584391, 2024). "iNK-CTLs can exert cytotoxicity through the Fas/FasL pathway, the TNF-α pathway, and the granzyme and perforin pathways of tumor cells carrying CD1d molecules." (PMID 38515134, 2024). "Tumour cells expressing CD1d are mainly of myelomonocytic and B cell origin, while very few solid tumours express CD1d." (PMID 38579449, 2024). "For this reason, we used MDA-MB-231.hVCAM1.hCD1d tumor cells with median CD1d expression level, and used CD1d high expressing Hela.hCD1d cells to mimic DCs with high antigen presenting capacity." (PMID 38332012, 2024). "Together, our data demonstrate that interfering with VCAM1-CD49d signaling enhances anti-tumor efficacy of iNKT cells irrespective the expression of CD1d or VCAM1 by tumor cells." (PMID 38332012, 2024).
tumor (continued). "Mechanistically, CD1d, expressed on macrophages, interferes with tumor infiltration of iNKT cells and iNKT-DC interactions but does not influence their intratumoral motility." (PMID 38332012, 2024). "The CD1d-Vδ2 bsTCE, or LAVA-051, has shown anti-tumor potential against hematological malignancies expressing CD1d in preclinical models." (PMID 38576617, 2024). "For instance, CD1d interactions with the T-cell receptor on NKT(Natural killer T cell) cell surfaces allow lipid antigens to stimulate anti-tumor responses of NKT cells." (PMID 38181281, 2024). "Remarkably, even under conditions of high tumor burden and BCMA+CD1d− tumor cells, Allo/U15BCAR-NKT cells continued to effectively suppress tumor growth and achieved superior tumor clearance." (PMID 38584391, 2024). "The first synthetic analogue of α-GalCer (KRN7000) was first shown to exhibit NK-mediated anti-tumor effects, then shown to be a CD1d-restricted antigen for iNKT cells." (PMID 39669569, 2024). "Although these in vitro studies included addition of αGalCer, the iNKT cell TCR likely also interacts with CD1d loaded with endogenous tumor lipids." (PMID 39170618, 2024). "Known inherent anti-tumor activity against CD1d + tumors. iNKT cells can modulate myelomonocytic populations of tumor microenvironment to antagonize tumor progression." (PMID 38993780, 2024). "Our study proposes a combinational immunotherapy with iNKT cell transfer and VCAM1/CD49d antibody treatment, irrespective the VCAM1 expression and CD1d expression by tumor cells." (PMID 38332012, 2024). "While the relevance of these non-classical CD1d functions has been mainly investigated in vitro, some studies also support key roles for CD1d in controlling inflammation, infection or tumour progression in vivo." (PMID 38579449, 2024). "Conversely, CD1d expression in macrophages inhibits tumor infiltration of iNKT cells and interferes with iNKT-DC interactions as well as Th1 response in tumors." (PMID 38332012, 2024). "In summary, the inflamed subtype of HCC exhibited a notable presence of CD19+ cells accompanied by significant CD5+ and CD1d+ expression in the tumor area." (PMID 39611128, 2024). "Activated iNKT cells can directly kill CD1d+ tumor cells via their semi-invariant TCR through Fas/FasL interactions and secretion of cytotoxic granules." (PMID 39170618, 2024). "Given the fact that some tumor cells express CD1d molecule, we next generated CD1d expressing MDA-MB-231.hVCAM1.hCD1d cells." (PMID 38332012, 2024). "iNKT cells recognize aberrant cells, such as infected, damaged, senescent, and tumor cells that express a combination of lipid-CD1d molecules." (PMID 38515134, 2024). "Upon stimulation by α-GalCer/CD1d, iNKT cells not only exhibit direct killing activity against tumor cells but also modulate other immune cells to exhibit indirect antitumor activity." (PMID 38515134, 2024). "CD5+ and CD1d+ cells were abundant and spatially distributed in the different compartments of the tumor." (PMID 39611128, 2024). "Consistently, the metastatic potential of the mice model of breast cancer is inversely correlated with the expression of CD1d on tumor cells and the effectiveness of NKT cell recognition." (PMID 36769513, 2023). "In comparison, although we and other investigators have reported that tumors grew markedly slower in CD1d−/− mice than those in WT mice, WTMCGEP significantly accelerated tumor growth inhibition in such CD1d−/− mice." (PMID 37152373, 2023). "A remarkable, dose-dependent inhibition of tumor growth was observed in mice with admixed PBMCs treated with the CD1d-Vδ2 hu-bsTCE; tumor growth was only observed after discontinuation of bsTCE treatment." (PMID 36868236, 2023). "In co-cultures with CD1d+ tumor cell lines, the CD1d-Vδ2 bsTCE triggered type 1 NKT cells to secrete Th1 and Th2-type cytokines, including IL-2, IL-4, tumor necrosis factor (TNF), and interferon (IFN)-γ, whereas Vγ9Vδ2-T cells mainly secreted TNF and IFN-γ." (PMID 36868236, 2023).